CD4 (CD4 molecule)
Diseases named in the same sentence as CD4 in open-access papers (continued):
Sharing a sentence is not in itself a finding about the gene and the disease.
viral infection (continued). "Acute viral infections typically induce a CD4+ T cell response that is almost exclusively composed of Tfh and Th1 cells, in approximately equal proportion." (PMID 29951052, 2018). "With a distinct strategy, AGMs have also evolved to protect memory CD4+ T cells from viral infection." (PMID 29725327, 2018). "In response to viral infection, differentiation of activated CD4 T cells is directed towards an IFN-γ-producing subset, referred to as TH1, that also produces IL-2 and TNF-α and enhances cellular immune responses by CD8 T cells and macrophages." (PMID 29734372, 2018). "Cytotoxic CD4+ T cells have been well characterized in contexts of viral infections, where cytotoxic CD4+ T cells either utilize granzyme B and perforin or Fas–FasL interactions to mediate killing of infected cells." (PMID 29545791, 2018). "This permitted, in contrast to previous studies, to examine the function of TFH cells and LCMV-specific CD4 T cells during persistent viral infection beyond the mere induction of the virus-specific antibody response." (PMID 29887868, 2018). "All the patients who presented with verruca and recurrent herpes labialis had lymphopenia and low CD4 levels; therefore, individuals with recurrent viral infections must be evaluated for CVID." (PMID 29849668, 2018). "Following in vivo stimulation by viral infection, Ezh2 was potently induced after CD4+ T cell activation, even before cell division, similar to the induction of CD25." (PMID 30575739, 2018). "Since the number of CD4+ T cells was decreased in CerS2 null mouse liver, we examined levels of iNKT cells, which form a major fraction of hepatic CD4+ T cells and are involved in protection against pathogens, including viral infection." (PMID 29163475, 2017). "During chronic viral infection, both the CD4+ and CD8+ T cell responses are impaired by a dysfunctional or exhausted state characterized by diminished effector function and enhanced expression of inhibitory molecules in T cells." (PMID 28732506, 2017). "It is well established that CD4 T cells play a significant, often central, role in the immune response to viral infections." (PMID 28167943, 2017). "Although the role of IL-21 signaling in the CD4 T cell response to viral infection remains imperfectly defined." (PMID 29511486, 2017). "This review aims at summarizing currently available data about functional and therapeutic relevance of cytotoxic CD4+ T cells in the context of viral infections and virus-driven tumors." (PMID 28289418, 2017). "Detection of R5-tropic virus infection in CD4+ T lymphocytes was lower than that of X4-tropic virus infection, which should be due to a lower level of CCR5 expression than CXCR4 expression in CD4+ T lymphocytes." (PMID 28241053, 2017). "Previous studies have shown that the interaction between recombinant gp120 and CD4/coreceptors (CCR5 or CXCR4) enhances the early stage of viral infection." (PMID 28842659, 2017). "Of note, it has been shown in the course of a viral infection that by interacting with pre‐activated CD4 T cells, cDC1 constitute a platform for delivery of CD4 T cell help to CD8 T cells." (PMID 28935714, 2017). "CD4 CTLs have been detected mostly in virus infection models, suggesting that one of the main functions of CD4 CTLs is antiviral immunity." (PMID 28280496, 2017). "To further examine the changes in ATF4 expression in response to early viral infection, we expanded our analysis to in vitro primary human CD4+ T cells following HIV infection and measured the induction of ATF4 expression." (PMID 28465428, 2017). "Dual cytokine-producing CD4+ T cells also have been identified in models of autoimmunity and viral infection, and IFN-γ+/IL-17+ CD4+ T cells have been described in pathogenic post viral immune responses." (PMID 28129374, 2017). "CD4 T cells provide “help” that drives B cell activation and antibody production during responses to viral infection and immunization." (PMID 28723925, 2017).
viral infection (continued). "Although numerous studies have demonstrated the importance of TFH cells in GC reactions, little is known about the factors that drive TFH differentiation from naïve CD4+ T cells upon viral infection." (PMID 29186193, 2017). "In a subsequent study, the same group of investigators showed that only 5% of CD4+ T-cell depletion occurs through apoptosis, while the remaining 95% of quiescent lymphoid CD4+ T-cells die by caspase-1-mediated pyroptosis triggered by abortive viral infection." (PMID 28588579, 2017). "T-bet is one of the important transcription factors for cytotoxic CD8 and Th1 CD4 cell differentiation in response to viral infection." (PMID 28455436, 2017). "HLA class II molecules present peptides to CD4+ T cells (T helper cells) eliciting both cell-mediated and antibody responses to control viral infection." (PMID 29868224, 2017). "CD4 T regulatory cells (Tregs) are the major rheostat of immune homeostasis, in addition to suppressing cell mediated immunity to viral infections including HIV infection." (PMID 29267399, 2017). "CD4 T cells have been shown to play a vital role in limiting CD8 T cell exhaustion during chronic viral infection in B6 mice." (PMID 28715493, 2017). "IL-6 affects differentiation of CD4 T cells and can also modulate aspects of the innate immune response to viral infection." (PMID 28746373, 2017). "Although exhaustion of CD4+ and CD8+ T cells have been described by many clinical studies during chronic viral infection, we found that there were more CD4+ T cells expressing PD1 and CTLA4 compared to CD8+ T cells in this model." (PMID 28886065, 2017). "Follow-up data of the patients under study (i.e., HIV viral load and CD4+ T-cell counts) were obtained during the preparation of this report to evaluate the clinical progress of the viral infection." (PMID 29257103, 2017). "Activation of CD8 and CD4 T-cells has been extensively described in several viral infections and likely represents the efforts of the immune system to counteract viral replication." (PMID 28740159, 2017). "It is still unclear how much this reprogramming mechanism is involved in CD4 CTL differentiation during virus infection." (PMID 28280496, 2017). "We further consider the cells that are the predominant targets of this effector subset and describe the viral infections in which CD4 cytotoxic T lymphocytes have been shown to play a protective or pathologic role." (PMID 28167943, 2017). "Functional envelope clones capable of free-virus infection were isolated from both the CD4-DARPin treated and control culture supernatants." (PMID 28264054, 2017). "Recent studies have identified a PD-L1-expressing CD4 T-cell population as also being capable of suppressing IFN-γ in viral infection and blocking PD-L1 in vivo resulted in reductions in viral load." (PMID 28871261, 2017). "An effective presentation of viral antigens by HLA class I and II molecules to CD8+ and CD4+ T cells is essential for an adequate immune response to viral infection." (PMID 29138492, 2017). "Recently, CD4+ T cells with cytotoxic features have been identified in PBMC from patients with chronic viral infections." (PMID 28649242, 2017). "After viral infection, effector CD4+ T cells differentiate into TCF-1highBlimp-1low Tfh and TCF-1lowBlimp-1high Th1 cells." (PMID 28732506, 2017). "More specifically, PJA2 is well expressed in CD4+ Jurkat and Sup-T1 T cells, highlighting that this ubiquitin ligase can regulate Tat activity during natural viral infection." (PMID 28345603, 2017). "Chronic viral infection drives CD4 T cell conversion from a Th1 phenotype critical for viral clearance to a T follicular helper (Tfh) phenotype." (PMID 28715493, 2017). "In response to viral infections and inflammatory stimuli, mDC1s activates CD4+ T lymphocytes and possess the capacity to promote Treg differetiation." (PMID 29047360, 2017).
viral infection (continued). "Accordingly, future T cell phenotype studies should take into account chronic viral infections (i.e. CMV) for CD4+TEM subset characterization." (PMID 28615072, 2017). "In this study, we found the interaction between gp120 and CD4/coreceptors also benefits the late stage of viral infection." (PMID 28842659, 2017). "This possible scenario in which high viral loads impair virus-specific CD4+ T cell responses has been reported for other viral infections." (PMID 28662714, 2017). "One potential explanation for this is the observation that exhaustion of CD4+ T cells becomes apparent earlier during chronic viral infection as compared to CD8+ T cells." (PMID 28886065, 2017). "Persistence of viral infections includes a complete reprogramming of the local immune response, attenuation of production of type 1 interferon, and local alteration of the CD4+/CD8+ T cell balance." (PMID 28231295, 2017). "We first quantified R10015 inhibition of the early steps of HIV infection of CD4 T cells, in which cells were exposed to R10015 only briefly during viral infection; R10015 was removed from the infection culture following infection." (PMID 28381571, 2017). "In chronic HIV infection there exists a reservoir of latent, transcriptionally silent viral infection within the resting memory CD4+ T cell compartment and specific myeloid lineage cells (e.g., CD14+/CD16+ monocytes) [reviewed in Ref." (PMID 28649242, 2017). "Taken together, M2e5x VLP-mediated immunity is partially dependent on CD8 T cells during the secondary heterosubtypic virus infection whereas primary infection-mediated immunity is related with both CD4 and CD8 T cells." (PMID 29276514, 2017). "The pro-Th2 cytokine IL-33 is now emerging as an important Th1 cytokine-IFN-γ inducer in murine CD4+ T cells that is essential for protective cell-mediated immunity against viral infection in mice." (PMID 26688508, 2016). "These CD4+ T cell populations changed in numbers and distribution during the course of viral infection." (PMID 26996968, 2016). "Herein, both the CD8+ and CD4+ T cells were involved in an IFN-mediated antiviral immune response against viral infection." (PMID 27150912, 2016). "IFN-γ, a key Th1 cytokine with immunomodulatory effects, mediates cellular immunity against virus infections by controlling the differentiation of naïve CD4+ cells for production of CD4+ cells." (PMID 26848967, 2016). "A primary target for viral infection is the gastrointestinal tract, which is a reservoir of CD4+ T cells." (PMID 27256449, 2016). "Although macrophages and CD4+ T cells are both major targets of HIV-1, the susceptibility to viral infection is different in the two cell types and depends on the activation status of the cells." (PMID 27089879, 2016). "IFNγ is the canonical Th1 cytokine that is crucial for a cellular immune response as it controls the differentiation of naïve CD4+ T cells into Th1 effectors, which mediate cellular immunity against viral infections." (PMID 26653678, 2016). "Tetherin+ DCs also more potently stimulated virus-specific CD4+ T cells compared to Tetherin KO DCs ex vivo despite similar virus infection levels." (PMID 26846717, 2016). "In Patient 3 (Pt-3), however, the memory subsets (TCM and TTM) bore only a small proportion of infected CD4+ T cells, and the TN subpopulation was the main target of viral infection (>80 % at all the time points analyzed)." (PMID 27484989, 2016). "The stoichiometry of syncytia formation is quite different from virus infection since there are many more Env (and CD4/coreceptors) molecules spread across the cell surface compared to the limited number (approximately 10) of Env molecules on a single virion." (PMID 26816344, 2016). "An alternative and distinct subset of CD4+ T cells exerting cytolytic activity has been occasionally described over the last 30 years, mostly in the setting of viral infection." (PMID 26973647, 2016).
viral infection (continued). "Although presentation of viral antigens relies classically on MHC class I molecules, sufficient T-cell CD4+ engagement is an important predictor of outcome for several viral infectious diseases, including hepatitis A and B, and influenza." (PMID 27812212, 2016). "Acute viral infections, including the 17D-based vaccines, result in the proliferation of virus-specific CD4+ and CD8+ T cells responding to diverse epitopes." (PMID 27463517, 2016). "The deletion of Blimp-1 from CD4+ T cells leads to augmented Tfh cell formation in response to viral infection as this transcription factor directly suppresses Bcl-6 expression." (PMID 31557986, 2016). "These DC are a potential source of new viral infection of both resident follicular helper T cells and circulating CD4+ T cells like central memory and naïve CD4+ T cells." (PMID 26858771, 2016). "Type I IFNs have also been shown to indirectly regulate Th1 CD4 T cell activity during acutely lethal experimental cerebral malaria and acute virus infection." (PMID 27732671, 2016). "Examination of the HSV-specific gDT-II cells between and around the hair follicles by two-photon microscopy after virus infection showed that CD4+ T cells in both locations were motile and migrating rapidly." (PMID 27160938, 2016). "Cytolytic CD4+ T cells have also been described as potent immune effectors in protection against many viral infections, including CMV, Epstein-Barr Virus, Influenza and HIV." (PMID 27662621, 2016). "More recent data have provided evidence that CD4 CTL can utilize the perforin–granzyme pathway of target cell killing to act as primary lytic effectors for many viral infections including mouse gamma herpes virus, mouse pox, and IAV." (PMID 27014272, 2016). "Systems biology analysis of human responses to yellow fever vaccine induced a type I interferon-mediated response comparable to the MAVS-mediated CD4+ T cell response we present, including upregulation of IRF7 and various ISG including MxB, Viperin, and ISG56." (PMID 26849062, 2016). "Other cell types such as epithelial cells can be induced to upregulate the expression of MHC class II molecules following viral infection and potentially become additional targets for cytotoxic CD4 T cells." (PMID 28003809, 2016). "We now appreciate a greater role for CD4 CTL as direct effectors in viral infections and antitumor immunity through their ability to acquire perforin-mediated cytolytic activity and contribution to lysis of virally infected targets or tumors." (PMID 27014272, 2016). "A cytotoxic CD8 T cell response is important for the control of viral replication, especially in chronic or persistent viral infections, but CD4 T cells also play a crucial role in the induction of CD8 T cell responses." (PMID 26909080, 2016). "We also performed the GO analysis of m6A-modified cellular genes in HIV-1 infected Jurkat cells and primary CD4+ T cells and found numerous genes with known functions in viral infection-related pathways." (PMID 27371828, 2016). "Earlier autophagy has been implied to be essential for HLA-DR loading with intracellular material relevant for CD4+ T cells to monitor cellular virus infection, transformation (62, –64) or stress, or to shape their self-tolerance." (PMID 26764012, 2016). "To better understand the specification of diverse CD4 T cell subtypes during viral infection, we compared the gene expression profiles of Tfh and Th1 effector CD4 T cell subsets that formed during acute LCMV infection." (PMID 25569154, 2015). "In the future, mutant VACVs will allow aspects of the mechanisms of CD8+ and CD4+ T-cell responses during acute virus infection to be dissected." (PMID 25382035, 2015). "Spatiotemporal interactions between B cells, CD4 T cells, and dendritic cells (DCs) are critical during early viral infection and likely determine the orientation and nature of the immune response." (PMID 26042124, 2015).
viral infection (continued). "Viral infection can induce CD25 expression in lymphocytes or directly activate CD4+CD25+ cells, potentially contributing to immune dysfunction." (PMID 25803101, 2015). "Intriguingly, Treg cells appear to play a central role in anti-viral effector CD4 T cell fate decisions during viral infections due to their production of TGF-β and ability to consume IL-2." (PMID 25569154, 2015). "Experimental data from numerous systems demonstrate that CD8 and CD4 T cell responses co-operate to control viral infections by production of cytokines as well as inducing target cell lysis." (PMID 26322025, 2015). "In that experiment, SAMHD1 was reported to block virus infection in resting human CD4+ T lymphocytes unless SIVmac239 Vpx was co-packaged into an HIV-1 expressing GFP construct." (PMID 25996507, 2015). "Resistance to viral infection was also observed in primary human CD4+ T-cells stably expressing Myr(+)AnkGAG1D4, and challenged with HIV-1, SIVmac, or SHIV." (PMID 26305555, 2015). "We believe that the viral infection led those regulatory CD4+CD25+ cells to migrate to the periphery away from their natural origin to effect their suppressive roles." (PMID 25803101, 2015). "Variables related to renal function deterioration older age, presence of diabetes, HTA, bad control of the viral infection, and low CD4 lymphocytes were similar to those described in our eVIHa all cohort and previously in studies on European cohorts." (PMID 26064679, 2015). "There is increasing evidence that cellular miRNAs play critical roles in HIV-1 pathogenesis including promoting viral infection, latency in resting CD4 T cells and mediating cell-intrinsic HIV-1 resistance." (PMID 26108174, 2015). "Despite the importance of CD4+T cells during virus infection, CD4+T-cell immunity towards hantaviruses remains limited." (PMID 25836633, 2015). "Th17 cells are a unique mucosal CD4 effector population responsible for protection from extracellular bacteria, fungi and viral infection at mucosal surfaces, and these cells are rapidly depleted in HIV infection." (PMID 26544970, 2015). "Of note, STAT-6−/− mice infected with WT virus had the lowest number of IFN-γ producing CD4 T cells but it was the only strain in which mutant virus infection increased numbers significantly by nearly 90-fold." (PMID 25751266, 2015). "As a functional readout for SNAT1 downregulation in the context of viral infection, we examined the effect of Vpu expression on proliferation of primary human CD4+ T cells." (PMID 26439863, 2015). "In general, an upregulated transcriptome profile was seen in both MT-2 and primary infected CD4+ T cells, emphasizing the highly active and dynamic process of viral infection." (PMID 25809782, 2015). "Recent studies have demonstrated that CD4+T cells are also essential for the effective clearance of viral infections." (PMID 25836633, 2015). "Absence of vIFN-γbp during infection had minimal effects on CD4 T cell responses with the exception of STAT-6−/− mice in which mutant virus infection significantly increased IFN-γ+ CD4 T cell numbers." (PMID 25751266, 2015). "Diterpenes can down-modulate the expression of cell surface receptors that are known to mediate HIV attachment and entry and can potentially prevent the spread of viral infection to bystander CD4+ T cells." (PMID 26225771, 2015). "During a viral infection, a type of immune cell in the host can specialize into two different types of cells to help fight the virus: T helper 1 cells and CD4 T follicular helper cells." (PMID 25569154, 2015). "It is now recognized that the gastrointestinal (GI) tract is a major site of HIV-1 and SIV replication and the number of CD4+ T cells is markedly reduced during all phases of the virus infection." (PMID 25996507, 2015). "Single IFN-γ+ CD4+ T cells are associated with viral primary infection with high viral load, while chronic viral infection is related to single IL-2+ or IL-2+IFN-γ+ CD4+ T cell responses." (PMID 25822536, 2015).